HSPA8 (heat shock protein family A (Hsp70) member 8)
Diseases named in the same sentence as HSPA8 in open-access papers (continued):
Sharing a sentence is not in itself a finding about the gene and the disease.
lupus (16 papers, 2009 to 2023). "In this respect, as already mentioned, cell surface localized HSPA8 plays an active role in the immune mechanisms associated to systemic lupus erythematosus." (PMID 28934328, 2017). "For example, flow cytometry research has clarified increased expression of HSPA8 on B cell, T cells, and specifically activated T cells in the spleen of MRL/LPR lupus susceptible mice." (PMID 36452344, 2022). "The CMA markers LAMP-2A and HSPA8 were overexpressed, in spleenic B cells of lupus-prone MRL/LPR mice, and CMA-associated lysosomes were 1.6-fold higher than non-lupus-prone CBA/J mice." (PMID 36733375, 2022). "Some defects have also been described in lupus regarding chaperone-mediated autophagy (CMA), a selective autophagic pathway mediated by the chaperones HSPA8/HSC70 and HSP90AA1, and by the lysosome-associated membrane protein 2A (LAMP2A)." (PMID 33092174, 2020). "Flow cytometry studies show, for example, that in the spleen of MRL/lpr lupus-prone mice, the expression of HSPA8 is raised at the surface of the B cells, T cells and specially-activated T cells, and the CD11b+Gr-1+ granulocytes/macrophages." (PMID 31394830, 2019). "Using the non-metastatic fibroblastoid cell line MRL/N-1 derived from a MRL/MpTn-gld/gld lupus-prone mouse, we discovered that P140 treatment neutralized the egress of HSPA8 from nucleus to cytoplasm in the cell recovery phase." (PMID 30429537, 2018). "It is also supported by in vivo data demonstrating that upon treatment of MRL/lpr mice with the P140 peptide, the levels of two key CMA components, namely LAMP-2A and HSPA8, which are over-expressed in lupus mice are significantly decreased in B cells of treated mice." (PMID 26042127, 2015). "For the specific inhibition of CMA, namely the interaction with HSPA8, a peptide called P140 was discovered a few years ago, successfully undergoing clinical trials for the treatment of systemic lupus erythematosus, which may represent a promising therapeutic option in the future." (PMID 34685711, 2021). "It acts as an immunomodulator that interferes with excessive immune responses occurring in lupus and other autoimmune diseases, and considerably slows the pathophysiological process down It was shown to directly interact with HSPA8 and to inhibit the chaperone activity of the latter." (PMID 31394830, 2019). "P140, a synthetic peptide evaluated in phase-III clinical trials for lupus, binds HSPA8/HSC70 chaperone protein." (PMID 35720371, 2022). "In the present study, we identified HSPA8 in subgroup III, further supporting a possible link between members of this subgroup and lupus neuropsychiatric symptoms." (PMID 36595784, 2022). "For example, flow cytometry studies showed that the expression of HSPA8 was increased in the splenic B and T cells of MRL/MpTn-gld/gld lupus-prone mice." (PMID 34663331, 2021). "Furthermore, the levels of HSPA8 chaperone protein and LAMP2A, which are both overexpressed in MRL/lpr B cells, were found to be corrected after P140 treatment of MRL/lpr lupus-prone mice." (PMID 34572117, 2021). "This might indicate that in lupus conditions, CMA− lysosomes retain more HSPA8 in their lumen to become more active in CMA, possibly to compensate for the overall higher lysosomal fragility." (PMID 33092174, 2020). "However, likely as a matter of consequence resulting from its interaction with the HSPA8 chaperone, it strongly reduces the overexpression of MHCII molecules on lupus B cells acting as antigen-presenting cells, and hampers peptide–MHCII molecule loading in late lysosomal vesicles (MIIC compartment)." (PMID 31394830, 2019). "It is therefore possible that a modification in the stability of LAMP-2A occurs in the lupus model, and since HSP90 is involved in the stabilization of LAMP-2A, the weaker stability of LAMP-2A could in fact result from the effect of P140 with the HSPA8 heterocomplex containing HSP90." (PMID 26042127, 2015).
hepatocellular carcinoma (15 papers, 2017 to 2025). A malignant tumor that arises from hepatocytes. "In HBV-related hepatocellular carcinoma, HSPA8 appears to exert dual functions, potentially regulating viral replication and ferroptosis pathways." (PMID 41471859, 2025). "For instance, miR-26b-5p inhibites cell proliferation and induces apoptosis in multiple myeloma cells by targeting JAG1, and maintains the stemness of hepatocellular carcinoma cells by inhibiting HSC71/HSPA8." (PMID 34488538, 2021). "HSPA8 is highly expressed in hepatocellular carcinoma, prostate cancer and other cancer." (PMID 36452344, 2022). "In addition, researchers have found that HSPA8 is highly expressed in different cancer cells, such as hepatocellular cancer and endometrial cancer." (PMID 36452344, 2022). "Besides, HSPA8 high expression has been identified in various cancer cells, including hepatocellular carcinoma and endometrial carcinoma, and is involved in cancer cell growth and regulating the autophagy in tumor cells." (PMID 33926391, 2021). "HSPA8 could regulate the cell viability in pancreatic cancer cells and serve as a molecular target in human hepatocellular carcinoma." (PMID 34412642, 2021). "For instance, in hepatocellular carcinoma (HCC), HSPA8 functions as a co‐activator of the transcription factor ETV4, leading to the upregulation of PHLDA2, thereby facilitating the progression of liver cancer." (PMID 40099939, 2025). "HSPA5 and HSPA8 were in the center of the PPI network, suggesting that they are involved in the occurrence and development of hepatocellular carcinoma via several mechanisms." (PMID 34059060, 2021).
liver cancer (14 papers, 2020 to 2025). An epithelial or non-epithelial malignant neoplasm that arises from the liver. "Here, we found that HSPA8 is significantly upregulated in liver cancer, associated with poor prognosis." (PMID 39047638, 2024). "In cases of liver cancer linked to viral hepatitis, HBx‐induced HSPA8 enhances HBV replication and inhibits ferroptosis, thereby facilitating the progression of liver cancer." (PMID 40099939, 2025). "TCGA and CPTAC databases showed that HSPA8 mRNA and protein levels were notably increased in liver cancer tissues compared to those in normal tissues." (PMID 39047638, 2024). "Consistent with our study, downregulating HSPA8 upon sericin treatment possibly helps to prevent liver cancer." (PMID 38443583, 2024). "Taken together, these data suggested that HSPA8 was responsible for the regulatory effects of LACTB on ferroptosis in liver cancer cells." (PMID 39047638, 2024). "For example, HSPA8 was triggered to advance liver cancer development by boosting HBV replication and inhibiting ferroptosis." (PMID 38440732, 2024). "HSPA8 suppressed ferroptosis in liver cancer cells by upregulating the expression of SLC7A11/GPX4, decreasing erastin-mediated reactive oxygen species, and accumulating Fe2+ in cells in vitro and in vivo." (PMID 37840106, 2023). "The role of HSPA8 is expressed abnormally in early liver cancer, and its expression increases with cancer initiation and progression." (PMID 34178637, 2021). "Moreover, HBX directly activates the transcription factor HSF1 to upregulate the expression of HSPA8, inhibiting ferroptosis in liver cancer cells." (PMID 39532842, 2024). "Recent studies have shown that HSPA8 can inhibit ferroptosis to support liver cancer progression." (PMID 38420434, 2024). "So, HSPA8 detection may improve early detection of liver cancer sensitive indicators, but whether and how HSPA8 is involved in cancer initiation and development has been explored." (PMID 34178637, 2021). "Upregulation of HSPA8 and SEC61A1 affected hepatocarcinogenesis, identifying HSPA8 and SEC61A1 as potential therapeutic targets in liver cancer." (PMID 39593796, 2024). "Overexpression of HSPA8 notably abolishes the antitumour effect of LACTB, suggesting that HSPA8 is an oncogene in liver cancer." (PMID 39047638, 2024). "Heat shock protein family A member 8 (HSPA8) serves as a pivotal host factor in regulating Hepatitis B virus (HBV) replication and ferroptosis in liver cancer, suppressing ferroptosis by upregulating the expression of SLC7A11/GPX4 and reducing ROS and Fe2+ accumulation." (PMID 39600338, 2024). "Several studies have shown that HSPA8 inhibits ferroptosis by promoting SLC7A11/GSH/GPX4 signalling and inhibiting NCOA4-mediated ferritinophagy, We verified the effects of HSPA8 in liver cancer and found that LACTB promotes ferroptosis by regulating HSPA8-mediated ferroptosis-related signalling." (PMID 39047638, 2024).
colorectal cancer (12 papers, 2014 to 2026). A primary or metastatic malignant neoplasm that affects the colon or rectum. "Recent research indicates that HSPA8 enhances the progression of BRAF V600E colorectal cancer by activating Wnt/β‐Catenin signalling through CMA‐mediated degradation of CAV1." (PMID 40099939, 2025). "Upregulated heat shock 70 kDa protein 8 (HSPA8) predicts poor prognosis of BRAF V600E colorectal cancer." (PMID 37973552, 2024). "Notably, HSPA8 inhibitor VER155008 sensitizes BRAF V600E colorectal cancer to targeted drugs, which offers potential therapeutic strategies." (PMID 37973552, 2024). "Therefore, our SILAC results suggest that Hspa8 may play an important role in colorectal cancer and that its function could be independent of its role as a chaperone." (PMID 25502805, 2014).
melanoma (12 papers, 2013 to 2025). A malignant, usually aggressive tumor composed of atypical, neoplastic melanocytes. "The different response rates to BRAF V600E‐targeted drugs between BRAF V600E‐mutated melanoma and CRC, and the differential expression pattern of HSPA8 and MYC were consistent with our findings." (PMID 37973552, 2024). "Similar conclusion was also drawn for HSC70 after analyzing the expression levels of HSPA8 (coding HSC70) in patients in a melanoma cohort and their response to anti-PD-1 immunotherapy." (PMID 37640708, 2023). "To provide further information about the molecular mechanisms of SPANX-A/D in the promotion of tumorigenic processes, we evaluated the expression of Lamin A/C and HSPA8 in SPANX knockdowned melanoma cells (A375SPANX-KD)." (PMID 33574425, 2021). "Fourteen overlapping targets (GSK3B, MAPK1, HSPA8, VEGFA, FGF2, MTOR, and so on) were considered potential targets for the treatment of melanoma with salidroside." (PMID 40708947, 2025). "Under standard conditions (37 °C), melanoma cells were characterized by a high level (>0.04) of HSPD1 (HSP60), HSPA8 (HSP70), and HSP90AB1 (HSP90), and a medium level (0.02–0.04) of HSPB1 (HSP27), HSPA9 (HSP70), and AHSA1 (HSP90)." (PMID 37886980, 2023). "A core group of differentially expressed genes (FTH1, FTL, HSPA8, HSP90AA1, and HSP90B1) was recurrently identified within significantly enriched pathways across TCGA melanoma samples and clinical cohorts." (PMID 32296058, 2020).
glioma (11 papers, 2010 to 2024). A benign or malignant brain and spinal cord tumor that arises from glial cells (astrocytes, oligodendrocytes, ependymal cells). "Studies have shown HSPA8 expression is correlated with progression of gliomas." (PMID 36499281, 2022). "In addition to the constitutive expression of Hsc70 (HSPA8) through FAK and Src phosphorylation, it is also pivotal to dormant glioma cell reactivation to migration and invasion." (PMID 38994941, 2024).
ovarian carcinoma (10 papers, 2016 to 2025). A malignant neoplasm originating from the surface ovarian epithelium. "In the ovarian cancer tumor microenvironment, HSPA8 is implicated in modulating the immune response of monocytes/macrophages." (PMID 38166541, 2024). "A study on ovarian cancer found that degradation of HK2 occurred following the recognition of HK2-exposed KFERQ motifs by HSPA8 under conditions of cellular glucose deficiency." (PMID 37509689, 2023). "In ovarian cancer, ClpP is stabilized by HSPA8, a chaperone protein belonging to the HSP70 family, and contributes to cisplatin resistance, indicating a potential role in the regulation of chemoresistance." (PMID 41155556, 2025). "Taken together, our findings suggest that HSPA8-mediated stability of the CLPP protein regulates mitochondrial autophagy in DDP-resistant ovarian cancer cells." (PMID 38419499, 2024). "Our study reveals a novel regulatory axis of DDP resistance in ovarian cancer cells and suggests promising targets (i.e., HSPA8, CLPP, and mitochondrial protein homeostasis) for overcoming DDP resistance." (PMID 38419499, 2024). "Taken together, these results suggest that HSPA8 mediates cisplatin-resistant ovarian cancer cell phenotypes via CLPP-dependent signaling." (PMID 38419499, 2024). "Similarly, HSPA8 reduces CLPP protein stability in ovarian cancer cells and affects ovarian cancer cell drug resistance and survival via CLPP." (PMID 39578715, 2024). "The dynamic effects of the HSPA8/CLPP axis in ovarian cancer cells are also examined." (PMID 38419499, 2024). "In addition, we further investigated the effects of HSPA8 on ovarian cancer cells." (PMID 38419499, 2024). "Kaplan–Meier curve analysis revealed a significant correlation (p < 0.05) between low expression of HSP90AA1, HSPA8, PSMA5, and SOD1 and prolonged overall survival (OS) in ovarian cancer patients." (PMID 38166541, 2024). "Published proteomics and molecular biology studies suggest up-regulation of ACTN4, CRKL, GELS, HSPA8, talin-1, tubulins and WDR1 in ovarian cancer." (PMID 29344361, 2018). "We previously identified DEGs after transfection of FUT1 gene in ovarian cancer CAOV3 cell line, and found that the endoplasmic ERS-related gene HSPA8 was significantly changed, indicating that Lewis y may be involved in the ERS process." (PMID 36544104, 2022).
diabetes (9 papers, 2018 to 2024). "HspA8 lies within the borders of the Idd2 interval and evidence is suggesting that it is the ideal candidate gene affecting diabetes-related phenotypes within this QTL." (PMID 29867058, 2018). "Four proteins were markedly under-expressed (Hsp60, HspA8, TUBA1A, and ENO1) and linked to the pathogenesis of diabetes or post-translationally modified by O-GlcNAc." (PMID 29867058, 2018). "In particular, beta cells of diabetics exhibited decreased expression of genes encoding molecular chaperones belonging to the heat shock families Hsp70 (HSPA1B, HSPA7, and HSPA8) and Hsp90 (HSP90AA1 and HSP90AB1) as well as co-chaperones (BAG3 and ST13) and nucleoporins (NDC1, NUP160, and POM121C)." (PMID 37569434, 2023). "The level of HSPA8 was lower in T2D at baseline, in accordance with those reporting lower HSP70 levels in diabetes, and decreased following hypoglycemia compared with controls." (PMID 34831332, 2021). "Changes in the expression of related HSPs (HSPA8, HSP90AA1, and HSPA5,) have been confirmed in complications of diabetes and are functionally related to hyperglycemia-induced cell damage." (PMID 32851081, 2020). "In conclusion, these results suggest a significant increase in HSP90AA1 and HSPA8 concomitant with diabetes, and SREBF2 and GTAT2 may regulate the expression of HSP90AA1 and HSPA8." (PMID 38166541, 2024). "The clinical relevance of heat shock proteins in diabetes is further evidenced by studies showing higher levels of HSP70, HSP27, HSPA5, and HSPA8 in target organs affected by diabetic complications, as identified through this systematic review and meta-analysis." (PMID 39765892, 2024). "Through the PPI network screening, it was found that 5 key genes (YWHAZ, HNRNPA1, HSPA8, HSP90AA1, and HSPA5) obtained through protein interactions may provide new ideas for the treatment of diabetes." (PMID 32851081, 2020). "It was also revealed that HspA8 is upregulated in spleens of Non-obese diabetic mice as compared to controls with decreased incidence of insulitis and diabetes." (PMID 29867058, 2018).
acute myeloid leukemia (8 papers, 2021 to 2024). Acute myeloid leukemia (AML) is a group of neoplasms arising from precursor cells committed to the myeloid cell-line differentiation. "HSPA8 is highly expressed in acute myeloid leukemia, and patients with high HSPA8 expression tend to have a poor prognosis." (PMID 38419499, 2024). "Notably, high levels of HSPA8 were considered as a potential biomarker for endometrial cancer and as a prognostic factor for lower overall survival in acute myeloid leukemia." (PMID 34684727, 2021). "We found that HSPA8 was significantly upregulated in most cancer type while significantly downregulated in kidney renal clear cell carcinoma (KIRC), kidney renal papillary cell carcinoma (KIRP), and acute myeloid leukemia (LAML)." (PMID 38057779, 2023). "Likewise, in acute myeloid leukemia, it also was reported that HSPA8 had a negative relation with tumor suppressors." (PMID 38440732, 2024).
endometrial carcinoma (8 papers, 2019 to 2024). A malignant tumor arising from the epithelium that lines the cavity of the uterine body. "After validation, HSPA8 was considered the most upregulated protein, suggesting its potential as a diagnosis biomarker for early stages of endometrial cancer." (PMID 39194522, 2024). "In fact, HSPA8 has already been considered a therapeutic biomarker for early-stage endometrial cancer." (PMID 39194522, 2024). "siRNA of HSPA8 transfection into endometrial cancer cells significantly inhibited cell proliferation and growth and promoted apoptosis." (PMID 34059060, 2021). "In endometrial cancer, HSPA8 was also indicated as a potential therapeutic target." (PMID 39194522, 2024). "HSPA8 is key in the occurrence and development of endometrial carcinoma." (PMID 34059060, 2021). "Its depletion in RL-95-2 and HEC-1B cells was shown to suppress cell growth and promote apoptosis, suggesting that HspA8 could be a candidate biomarker for endometrial carcinoma." (PMID 31921692, 2019). "In endometrial cancer, two members of the heat shock proteins (HSP) family, HSPA5 and HSPA8, were proposed as good markers for diagnosis and prognosis." (PMID 39194522, 2024). "Differentially expressed proteins were allocated in KEGG pathways, identifying CCT7, HSPA8, PCBP2, LONP1, PFN1 and EEF2 as highly expressed in endometrial cancer." (PMID 39194522, 2024). "Some studies have shown that HSPA8 (HSC 70, HSP 71, HSP 71, or HSP 73) is overexpressed in endometrial carcinoma." (PMID 34059060, 2021).
prostate carcinoma (8 papers, 2011 to 2026). A carcinoma that arises from epithelial cells of the prostate gland. "In prostate cancer, the protein TPD52 has been observed to activate CMA through its interaction with HSPA8/HSC70, leading to enhanced substrate degradation." (PMID 39403142, 2024). "Lastly, unique hub-genes of naive CD4+ T-cells, such as HSPA8, are reported to be expressed in CD8+ T-cells in prostate cancer, while UBC, UBB, CTNNB1, and H3-3B are not reported, rendering them novel markers for naive CD4+ T-cells." (PMID 40906153, 2025).